SIRLNT (SIRT1 regulating lncRNA tumor promoter)
Synonyms: lncRNA-PRLB
Gene: Long non-coding RNA gene on chromosome 8 (40,298,697 to 40,373,444, reverse strand). Ensembl gene ENSG00000253802.
Diseases named in the same sentence as SIRLNT in open-access papers:
SIRLNT is named in the same sentence as 2 diseases in open-access papers, as found by Europe PMC text mining. Sharing a sentence is not in itself a finding about the gene and the disease. The quoted sentences say what the papers report.
breast carcinoma (2 papers, 2022 to 2024). "In conclusion, we discovered a new metabolism-related predictive risk model in breast cancer made up of 9 lncRNAs (SIRLNT, SIAH2-AS1, MIR205HG, USP30-AS1, MIR200CHG, TFAP2A-AS1, AP005131.2, AL031316.1, C6orf99)." (PMID 38347041, 2024). "lncRNA SIRLNT was recently discovered as a tumor promoter in breast cancer, by regulating the miR-4766-5p." (PMID 36419832, 2022).
tumor (2 papers, 2022 to 2024). "In lncRNA-Topic 4, which includes a set of 19 lncRNAs, SIRLNT (SIRT1 regulating lncRNA tumor promoter) has the top high probability of association with the topic (P(SIRLNT|lncRNA-Topic 4) = 0.6)." (PMID 38611028, 2024).